CTLA4 (cytotoxic T-lymphocyte associated protein 4)
Diseases named in the same sentence as CTLA4 in open-access papers (continued):
Sharing a sentence is not in itself a finding about the gene and the disease.
cancer (continued). "Consequently, immune checkpoint inhibitors like anti-CTLA-4, anti-PD-1, and anti-PD-L1 can bind to these inhibitory receptors, effectively restoring the immune response against cancer cells, making them suitable therapeutic targets." (PMID 40837737, 2025). "Two immune checkpoints have been targeted in therapeutic cancer management, CTLA4 and PD1." (PMID 40427188, 2025). "This marked discrepancy underscores that the role of CTLA-4 polymorphisms is not uniform across all cancer types but is likely highly context-dependent, influenced by the distinct immunobiology of the underlying illness." (PMID 41303553, 2025). "Recent development and use of inhibitors of ERK-signaling alone or in combination with revolutionary immune checkpoint inhibitors (ICI) targeting the receptors of cytotoxic T-lymphocyte-associated 4 (CTLA4) and programmed death-1 (PD1) proteins significantly improved survival of cancer patients." (PMID 40321772, 2025). "Using DNMTis in cancer treatment could raise the levels of CTLA-4 and PD-L1, which may help the cancer respond better to immune checkpoint inhibitor therapy." (PMID 40722734, 2025). "Similarly, cancer and autoimmune illnesses are influenced by immune checkpoint malfunction, specifically with regard to PD-1 and CTLA-4." (PMID 39996755, 2025). "When combined with immune checkpoint blockade therapy (anti‐CTLA‐4), it may further strengthen the suppression of cancer metastasis." (PMID 40135850, 2025). "However, significant associations were found between NKAIN1 protein expression in cancer nests and CTLA-4 (r = 0.246, P < 0.001) as well as PD-L1 expression (r = 0.215, P < 0.001) within cancer nests, demonstrating statistical significance." (PMID 41350575, 2025). "Particularly in immunologically deserted tumors, this approach could also prove synergistic with immune checkpoint inhibitors such as anti-PD-1 or anti-CTLA-4 antibodies, which have been shown to be effective in certain cancers in combination with RT." (PMID 40940937, 2025). "These two CTLA-4-specific antibodies have demonstrated robust antitumor activity and a favorable safety profile in the treatment of various cancers, and their combination with other therapies may further enhance clinical outcomes." (PMID 40317077, 2025). "Thus, the immune checkpoint blockades (ICBs), anti-CTLA-4 and anti-PD-L1, have been employed to suppress malignant tumors and have significantly improved patient survival rates." (PMID 40017598, 2025). "Ipilimumab blocks CTLA-4 enhancing T cell proliferation and activation to kill cancer cells." (PMID 39923010, 2025). "Currently, the two primary immune checkpoint targets in clinical practice are cytotoxic T-lymphocyte-associated protein 4 (CTLA-4) and the programmed cell death-1/programmed death-ligand 1 (PD-1/PDL-1) axis, with related antibodies being employed in a range of cancer therapies." (PMID 40842839, 2025). "The upregulation of immune checkpoint molecules occurs when cancer cells express proteins like cytotoxic T lymphocyte-associated protein 4 (CTLA-4) and programmed cell death ligand 1 (PD-L1) to bind their inhibitory receptors in immune cells, avoiding cancer cell destruction by T cells." (PMID 40282336, 2025). "Likewise, immune checkpoint inhibitors targeting PD-1, PD-L1, and CTLA-4 have revolutionized cancer therapy by reactivating T cells to combat malignant cells." (PMID 40364844, 2025). "Emerging evidence indicates that baseline use of certain concomitant drugs may affect the efficacy of immune checkpoint inhibitors (ICIs), including PD‐1, PD‐L1, and CTLA‐4 inhibitors, in patients with cancer." (PMID 41195639, 2025). "Overall, our findings indicated that the human anti-CTLA-4 antibody ipilimumab can modulate TA-HEVs when adequately Fc optimized, revealing a promising avenue for the therapeutic modulation of TA-HEVs in patients with cancer." (PMID 40460830, 2025).
cancer (continued). "The advent of immune checkpoint inhibitors (ICIs) targeting programmed death-1 (PD-1)/PD-ligand 1 (PD-L1) and cytotoxic T lymphocyte antigen 4 (CTLA-4) have revolutionized cancer therapy due to their ability to utilize the body’s own immune system to identify and destroy cancer cells." (PMID 40843765, 2025). "While combination therapy with PD-1/L1 and CTLA-4 inhibitors has proven effective in some cancers, bsAbs may offer improved PK, reduced systemic toxicity, and greater tumor-specific immune modulation." (PMID 40508202, 2025). "CTLA-4 blockade, using antibodies such as ipilimumab, has shown efficacy in cancer treatment." (PMID 40136652, 2025). "Similarly, a promising area of investigation in SETD2-mutated cancer is into immune checkpoint expression, such as HAVCR2, CTLA-4, or TIGIT or biomarkers such as CDCP1 and AXL." (PMID 41228333, 2025). "The association between the gut microbiota composition and clinical outcomes of immune checkpoint inhibitors (ICIs), such as inhibitors targeting cytotoxic T lymphocyte antigen-4 (CTLA-4), programmed cell death protein 1 (PD-1), and its ligand (PD-L1), was demonstrated in various cancer cohorts." (PMID 40869383, 2025). "Ipilimumab is another anti-CTLA-4 antibody, with proven antitumor activity against various cancers." (PMID 40405250, 2025). "By targeting molecules such as cytotoxic T-lymphocyte-associated antigen 4 (CTLA-4) and programmed death 1/programmed cell death ligand-1 (PD-1/PD-L1), ICIs enhance the immune system’s ability to identify and aggressively combat cancer cells." (PMID 41614820, 2025). "Therefore, aptamers are also known as “artificial antibodies”, and PD-L1/CTLA-4 aptamers have been used to replace antibodies and are widely used in cancer immunotherapy." (PMID 40033359, 2025). "This also sensitizes cancer cells to anti-PD-L1 and CTLA-4 immunotherapies." (PMID 40805190, 2025). "Two CTLA-4 specific fully human monoclonal antibodies, namely Tremelimumab and Ipilimumab, have so far reached the clinical phase of experimentation for the treatment of human cancer." (PMID 40317077, 2025). "Understanding the CTLA-4 signaling pathway and its role in immune evasion is vital for developing targeted immunotherapies aimed at enhancing the body’s natural defenses against cancer." (PMID 40739089, 2025). "For instance, patients with high levels of CD8+ T cell infiltration may benefit from immune checkpoint inhibitors, such as anti-PD-1 or anti-CTLA-4 therapies, which have shown efficacy in other cancers with a similar immune profile 71,72." (PMID 40657381, 2025). "The FDA has approved various ICIs for cancer therapy, including PD-1 receptor inhibitors (e.g., cemiplimab, nivolumab, and pembrolizumab), PD-L1 inhibitors (e.g., atezolizumab, avelumab, and durvalumab), and CTLA-4 inhibitors (ipilimumab and tremelimumab)." (PMID 40725844, 2025). "The characterization of immune infiltrates—such as TAMs, T lymphocytes, and myeloid-derived suppressor cells—as well as immune evasion mechanisms involving checkpoint molecules such as PD-1, PD-L1, and CTLA-4, is beginning to transform our approach to cancer therapy in animals." (PMID 41230456, 2025). "However, combination therapy of PD-1 or CTLA-4 inhibitor with TIL has displayed the abilities of positively improving such immunosuppressive TME therefore improves the anti-cancer effect on CCA cells." (PMID 41024300, 2025). "Thus, targeting CTLA-4 and PD-L1 with their specific therapeutics is crucial to promote T cell-directed immune reactivation against cancer." (PMID 41369373, 2025). "Similarly, ipilimumab is another humanized IgG1 mAb targeting CTLA‐4, which has demonstrated notable antitumor activity in several cancers." (PMID 41049266, 2025). "Therefore, immune checkpoint inhibitors, such as PD-1/PD-L1 and CTLA-4 blockers, have revolutionized cancer immunotherapy, being approved for many types of cancer." (PMID 39941775, 2025).
cancer (continued). "Cancer cells use checkpoint proteins such as PD-L1/PD-1 and CTLA-4 to turn off the T-cell response." (PMID 40927726, 2025). "Encouraging clinical results concerning treatments with these drugs in various forms of cancer endorse the idea that OSCC patients could benefit from the administration of ICIs targeting CTLA-4, too." (PMID 40725864, 2025). "Immune checkpoint inhibitors (ICIs) targeting cytotoxic T lymphocyte-associated antigen 4 (CTLA-4), programmed death 1 (PD-1), and PD ligand 1 (PD-L1) have revolutionized many cancers but have largely failed in PDAC, which exhibits primary resistance to monotherapy 10,11." (PMID 41323782, 2025). "The authors propose that combining antibodies targeting PD-L1 (to disrupt both trans PD-1/PD-L1 and cis PD-L1/CD80 interactions) with anti-CTLA-4 antibodies might further enhance T-cell reinvigoration in cancer patients." (PMID 41425548, 2025). "ICIs, including agents such as ipilimumab (anti–CTLA-4), nivolumab and pembrolizumab (anti–PD-1), and atezolizumab (anti–PD-L), have revolutionised the management of patients with cancer, by targeting immune checkpoint inhibitory pathways including CTLA-4, PD-L and PD-L1." (PMID 41227207, 2025). "We hypothesize that cancer survivors of dual ICI (CTLA-4 and PD-1 blockade) therapy potentially develop neurocognitive complications because of the disruption of immune regulatory networks during and post-ICI." (PMID 40313772, 2025). "Six of these—CD5, CTLA4, TIGIT, LAIR1, PDCD1, and TNFRSF14—encode proteins that have been identified as immune checkpoints, defined broadly as receptors on immune cells that are exploited by cancer cells to escape the immune response." (PMID 39887658, 2025). "A cycloheximide time course established that CTLA4 has an extremely short half-life (<1 h) in all three cell lines, which makes it one of the most short-lived transmembrane proteins described in human cancer cells." (PMID 39404738, 2025). "Due to limited publications regarding NLR in CTLA-4-treated cancer patients, we investigated whether a low NLR value was associated with an increased incidence of irAEs in this CTLA-4-treated cohort." (PMID 40563660, 2025). "Anti–CTLA-4 and anti–PD-1 monoclonal antibodies (mAbs) that antagonize the inhibitory function of these 2 molecules led to dramatic improvement of treatment for many types of cancers." (PMID 41026527, 2025). "Specific cancer types exhibited a significantly higher prevalence of certain TRAEs when stratified by the utilization of different checkpoint blockade therapies (anti-PD-1, anti-PD-L1, and anti-CTLA-4)." (PMID 39866435, 2025). "ICIs, including but not limited to anti-cytotoxic T-lymphocyte-associated protein 4 (CTLA-4), anti-programmed death-1 (PD-1) and anti-programmed death-1 ligand 1 (PD-L1), have demonstrated significant efficacy in the treatment of various cancers." (PMID 41236411, 2025). "In both healthy and cancer cells there is evidence for CTLA-4 cell-intrinsic signaling." (PMID 40175626, 2025). "We therefore analyzed the frequencies of autoreactive mature naive B cells from 4 patients with cancer before treatment, at 6 weeks — which is after 2 cycles of anti–CTLA-4 and anti–PD-1 combination therapy — and at 7 months, when only treated with anti–PD-1 for almost 5 months." (PMID 41026527, 2025). "ICIs, such as PD-1/PD-L1 and CTLA-4 inhibitors, have revolutionized cancer therapy." (PMID 40003691, 2025). "Treatment with ICB has improved clinical outcomes across numerous cancers, most notably metastatic melanoma (MM) where treatment with combination ICB to CTLA-4 (ipilimumab) and PD-1 (nivolumab) for MM is associated with extending median survival from months to beyond 5 years." (PMID 40712021, 2025). "Therefore, blocking CTLA-4 restores DC function, enhances T cell responses, and induces cancer cell apoptosis, presenting CTLA-4 as a therapeutic target in BC." (PMID 41550427, 2025). "The anti-cancer effect of PD-1 and CTLA-4 checkpoint inhibitors was enhanced." (PMID 40641524, 2025).
cancer (continued). "To the best of our knowledge, we couldn’t find other studies that explore the diagnostic significance in the form of sensitivity and specificity of combined PDL-1 and CTLA-4 expressions in cancer patients." (PMID 40108523, 2025). "Furthermore, invading lymphocytes often carry immune checkpoint molecules such as PD-1 and CTLA4, in addition to PD-L1 produced by cancer cells, which limits the anti-tumoral responses." (PMID 39127974, 2024). "The immune checkpoint inhibitors, the most thoroughly investigated class of immunotherapy, target programmed death 1 (PD-1) receptor, its ligand (PD-L1) or cytotoxic T-lymphocyte-associated protein 4 (CTLA-4), being its objective stimulate the immune response of patients against cancer cells." (PMID 39216661, 2024). "However, with reference to present oncology immune checkpoint inhibitors (ICIs) such as anti‐cytotoxic T lymphocyte associated protein 4, (CTLA‐4) and anti‐programmed cell death 1 (PD‐1) are better at treating cancer than traditional chemotherapy." (PMID 38333968, 2024). "Immunotherapy, specifically targeting immune checkpoint molecules like programmed cell death protein-1 (PD-1), programmed death-ligand 1 (PD-L1) inhibitors, and cytotoxic T lymphocyte-associated antigen-4 (CTLA-4), has revolutionized cancer treatment by enhancing the immune response against tumors." (PMID 38927885, 2024). "The ability of cancer to escape the immune system requires the presence of an immune-suppressive microenvironment frequently represented by the aberrant activation of immune checkpoints such as CTLA4, PD-1, and its ligand PD-1L." (PMID 39769153, 2024). "The most targeted checkpoints for cancer immunotherapy are CTLA-4 and PD-1." (PMID 39795946, 2024). "Besides programmed cell death protein 1 (PD-1) and cytotoxic T-lymphocyte associated protein 4, LAG3 is the third inhibitory receptor as a target for promoting anti-cancer responses and immunotherapies." (PMID 39211038, 2024). "Despite several CTLA-4 monoclonal antibody drugs have been recommended by the FDA for clinical trials in some cancers, they still face numerous challenges in terms of application such as complex structure, high immunogenicity, non-specifically binds to normal tissues and high production cost." (PMID 38824143, 2024). "This breakthrough established CTLA-4 as a significant target for cancer therapies." (PMID 39194710, 2024). "With an improved comprehension of immune checkpoint pathways and the advancement of novel immunotherapeutic approaches, the anticipation is that CTLA-4 inhibitors and their combined therapies will offer more efficacious treatment alternatives for a broader spectrum of cancer patients." (PMID 38903506, 2024). "Compared to ICI monotherapy, which occasionally demonstrates treatment resistance and limited efficacy, the dual blockade immunotherapy targeting PD-1/PD-L1 and CTLA-4 operates at different stages of T cell activation with synergistically enhancing immune responses against cancer cells." (PMID 39068460, 2024). "With anti-CTLA-4, the immune response may be enhanced at first, which should prompt the immune system to attack cancer cells efficiently." (PMID 39409171, 2024). "Since 2010, a revolution in cancer immunotherapy was started by the CTLA-4 antibody Ipilimumab." (PMID 38233492, 2024). "The overexpression of various ICPs, including programmed death protein-1 (PD-1) and cytotoxic T lymphocyte antigen-4 (CTLA-4) on T cells and their ligands (PD-L1 and CD80/86, respectively) on cancer cells, is associated with an uncontrolled growth of tumor cells and immune system idleness." (PMID 38835768, 2024). "Tremelimumab is another anti-CTLA-4 antibody, currently under investigation for several cancers." (PMID 38345654, 2024). "Notably, the introduction of T cell‐targeted ICIs, such as CTLA‐4 and PD‐1 or PD‐L1, represents a significant breakthrough in cancer treatment." (PMID 38594879, 2024).
cancer (continued). "Furthermore, anti-CTLA-4 therapy alone and/or with anti-PD-1 treatment has been shown to offer important therapeutic benefits to cancer patients, and it enhances antitumor immune activity due to an increase in the number of CD8+ and CD4+ TILs." (PMID 38612436, 2024). "By blocking CTLA-4 with ipilimumab, the immune system’s response to cancer cells is enhanced." (PMID 39399471, 2024). "The CTLA‐4 and PD‐1/PD‐L1 axes play critical roles in maintaining immune homeostasis, suppressing inflammatory responses, and potentially facilitating immune evasion by cancer cells." (PMID 38594879, 2024). "Immune checkpoint inhibitors (ICIs) have been studied for utility in cancer since the 1990s and became Food and Drug Administration (FDA) approved in 2011 with the agent ipilimumab, an ICI targeting cytotoxic T-lymphocyte-associated protein 4 (CTLA-4)." (PMID 39156347, 2024). "Ipilimumab, a CTLA-4 inhibitor, increases T cell activity against cancer cells by blocking CTLA-4." (PMID 39275127, 2024). "The abnormal expression of the CTLA-4 gene has been documented in many types of cancers, and it may contribute to the occurrence and progression of cancer." (PMID 39464701, 2024). "CTLA4 and PD-L1 inhibitors are effective in cancer treatment." (PMID 39132150, 2024). "Many medications targeting PD-1, PD-L1 or CTLA4, such as nivolumab and pembrolizumab, could be used to manage many types of cancer in the first-line therapy." (PMID 38345575, 2024). "Substances that suppress PD-1 and CTLA-4 could significantly enhance the treatment for advanced cancers." (PMID 38874512, 2024). "Moreover, increased ECM stiffness can amplify cancer’s immune evasion by altering the expression of immune checkpoint (IC) molecules like PD-L1, PD-1, and CTLA-4, potentially resulting in the failure of IC blockade (ICB) therapy." (PMID 38693104, 2024). "Immune checkpoint inhibitors, such as antibodies targeting cytotoxic T-lymphocyte-associated protein 4 (CTLA-4), programmed death-1 (PD-1), and programmed death-ligand 1 (PD-L1), have markedly improved cancer patient outcomes, but evoke several adverse effects, which often limit their clinical use." (PMID 38799466, 2024). "In addition, the JIP1 and CLN3 genes involved in resistance to chemo drugs and the PD-L1 and CTLA-4 genes acting on immune avoidance can also be targeted by siRNA for anti-cancer therapy." (PMID 39407665, 2024). "Monoclonal antibodies are used to target immune checkpoint molecules by inhibiting cytotoxic T lymphocyte-associated antigen-4 (CTLA-4), programmed cell death protein 1 (PD-1) and programmed cell death 1 ligand 1 (PD-L1), together results in a shift mode of treatment of malignant tumors." (PMID 39882247, 2024). "In addition, other studies have indicated an association of rs231775 with CTLA-4 expression and an effect on the affinity of CTLA-4 for B7-1 (CD80) in many cancers." (PMID 38723011, 2024). "In addition, inhibition of COPS5 by curcumin reduced the expression of PD-L1 and sensitized cancer cells to anti-CTLA4 treatment." (PMID 38466642, 2024). "Collectively, research to date has shown that Ruminococcaceae is greater in patients who respond to anti-PD-1 or anti-CTLA-4 treatments across a variety of cancer types and may have potential as a therapeutic adjuvant to ICI treatments." (PMID 38547865, 2024). "Ipilimumab and tremelimumab were approved for targeting CTLA-4 in several cancers." (PMID 38893154, 2024). "Antibodies targeting CTLA-4, PD-1, and its ligand PD-L1 are used in various cancer therapies." (PMID 38786018, 2024). "The role of soluble CTLA-4 in the immune regulation of cancer is poorly understood." (PMID 38053333, 2024). "Appropriate levels of SCFAs can reduce intestinal inflammatory responses and provide energy for intestinal epithelial cells, yet aberrant expression levels of SCFAs may affect the therapeutic efficacy of CTLA‐4 antibodies in cancer patients." (PMID 39503247, 2024).